RSPH6A (radial spoke head 6 homolog A)
Description:
Functions as part of radial spoke complexes in the axoneme of sperm flagella that play an important part in motility. The triple radial spokes (RS1, RS2 and RS3) are required to modulate beating of the sperm flagellum.
Synonyms: RSHL1; RSP4; RSP6; RSPH4B
Tractability: No criterion of Open Targets' tractability assessment is met for any kind of drug.
Gene: Protein-coding gene on chromosome 19 (45,795,713 to 45,815,308, reverse strand). Ensembl gene ENSG00000104941.
Subcellular location: Cytoplasm, cytoskeleton, flagellum axoneme
Gene Ontology:
Molecular function: protein binding
Biological process: axoneme assembly; cilium movement; flagellated sperm motility; manchette disassembly; sperm flagellum assembly; cilium assembly; cilium movement involved in cell motility
Cellular component: 9+2 motile cilium; axoneme; radial spoke; radial spoke head; sperm flagellum
Genetic constraint (gnomAD): Loss-of-function variants: 52 observed, 72.29 expected, observed/expected ratio (o/e) 0.72, 90% interval 0.57 to 0.91. The upper end of that interval is the gene's LOEUF score, 0.91, which puts it in group 3 of 6, group 1 being the genes least tolerant of losing a copy. Missense variants: 977 observed, 959.08 expected, observed/expected ratio (o/e) 1.02, 90% interval 0.97 to 1.07. Synonymous variants: 419 observed, 413.38 expected, observed/expected ratio (o/e) 1.01, 90% interval 0.94 to 1.1.
Homologues: Orthologues: chimpanzee RSPH6A (99% identical), macaque RSPH6A (95% identical), pig RSPH6A (80% identical), rat Rsph6a (76% identical), mouse Rsph6a (76% identical), guinea pig RSPH6A (53% identical), tropical clawed frog rsph6a (44% identical), zebrafish rsph4a (40% identical), Drosophila melanogaster Rsph4a (27% identical). Paralogues in human: RSPH4A (50% identical).
Diseases named in the same sentence as RSPH6A in open-access papers:
RSPH6A is named in the same sentence as 8 diseases in open-access papers, as found by Europe PMC text mining. Sharing a sentence is not in itself a finding about the gene and the disease. The quoted sentences say what the papers report.
male infertility (2 papers, 2020 to 2024). The inability of the male to effect fertilization of an ovum after a specified period of unprotected intercourse. "A compensatory gene for RSPH4A in the testis may be RSPH6A, which has not been associated with PCD, but depletion of the mouse Rsph6a is a reported cause of male infertility." (PMID 31781811, 2020). "Four recessive (TRIOBP, SLC26A4, GJB2, COL4A3) and one dominant (SOX10) for the deafness; six recessive genes (LRGUK, DNAH9, ARMC4, DNAH2, RSPH6A, and ACE) for male infertility can be conclusively ascribed." (PMID 38884051, 2024).
myotonic dystrophy type 1 (2 papers, 2022 to 2023). Steinert disease, also known as myotonic dystrophy type 1, is a muscle disease characterized by myotonia and by multiorgan damage that combines various degrees of muscle weakness, arrhythmia and/or cardiac conduction disorders, cataract, endocrine damage, sleep disorders and baldness. "In addition, in our previous study, we found that RSPH6A protein expression and localization were compromised in the SPZ of myotonic dystrophy type 1 (DM1) patients, causing impaired motility and fertility, producing the fertility defects observed in DM1 patients." (PMID 37795044, 2023).
primary ciliary dyskinesia (1 paper, 2024). A rare, genetically heterogeneous, primarily respiratory disorder characterized by chronic upper and lower respiratory tract disease. "LRGUK and RSPH6A genes are implicated earlier only in mice models, while the ARMC4 gene is implicated in chronic destructive airway diseases due to primary ciliary dyskinesia." (PMID 38884051, 2024). "Notably, genes like LRGUK and RSPH6A were previously implicated only in mice models, while the ARMC4 gene was implicated in chronic destructive airway diseases due to primary ciliary dyskinesia." (PMID 38884051, 2024).
RSPH6A also shares sentences with these, for which no sentence is quoted: asthenozoospermia (1 paper); deafness (1); infertile (1); myotonic dystrophy (1); tumor (1).